EGF (epidermal growth factor)
Diseases named in the same sentence as EGF in open-access papers (continued):
Sharing a sentence is not in itself a finding about the gene and the disease.
pancreatic cancer (continued). "As VEGF and EGF signalling pathways are inter‐related in pancreatic carcinogenesis, and AREG is an important prognostic factor of pancreatic cancer, we next focused on the possible role of the AREG pathway in the A platensis‐mediated therapeutic effects." (PMID 31957261, 2020). "Deimmunized Pseudomonas exotoxin cloned with human epidermal growth factor (EGF) and interleukin 4 showed activity against pancreatic cancer (PaCa-2) and selectively prevented metastasis." (PMID 29710857, 2018). "In the last decade, several studies attempted to demonstrate the connection between polymorphisms of angiogenesis-related factors (VEGF, VEGFR-2, RET, EGF, TGF-β) genes and pancreatic tumours." (PMID 28218664, 2017). "This clearly indicated a cytotoxic synergism between HisDianthin‐EGF and SO1861 on pancreatic tumor cell lines." (PMID 28755527, 2017). "Erlotinib is a well-known inhibitor of Epidermal Growth Factor (EGF) receptor (UniProtKB P00533) used to treat non-small cell lung cancer, pancreatic cancer and several other types of cancer." (PMID 28158609, 2017). "Epidermal growth factor (EGF) is upregulated in approximately 60% of adenocarcinomas of the pancreas, providing a rationale for the use of EGFR inhibitors in pancreatic carcinoma." (PMID 27438140, 2016). "Prolonged ERK phosphorylation has also been detected in pancreatic cancer cells due to the synergistic stimulation of NTS and EGF." (PMID 25644759, 2015). "In pancreatic cancer, miR-10b has been reported to enhance cell invasion by suppressing TIP30 expression and promoting EGF- and TGF-β-mediated pathways and it can be also considered as a novel diagnostic biomarker." (PMID 25330074, 2014). "Findings in this paper reveal that EGF transduces its signal through the AR/Src complex in HT1080 and various cancer-derived cell types, including colon and pancreatic cancer cells." (PMID 24130806, 2013). "High level of EGF and constitutive activation of the RAS-RAF-MEK-ERK pathway was found in pancreatic cancer." (PMID 22363658, 2012). "In pancreatic cancer, Ras/Raf-1/MAPK signaling is required for mediating growth factor-induced (such as epidermal growth factor) oncogenic effects." (PMID 22415852, 2012). "To investigate the possible mechanism for the regulation of DPEP1 expression in pancreatic cancer, we examined the levels of DPEP1 in Panc1 cells in response to EGF (30 nM), MEK1/2 inhibitor AZD6244 (1.5 μM) and PI3K inhibitor LY294002 (1.5 μM)." (PMID 22363658, 2012). "Taken together, these data strongly suggest that EGF induces the activation of ROCK via RhoA, and that the phosphorylation of cofilin and MLC by EGF occurs through ROCK in Panc1 pancreatic cancer cells." (PMID 21722395, 2011). "While EGF first stimulates the activation of EGFR, and subsequently induces pancreatic cancer cell proliferation, concurrent EGF-induced the activation of ROCK then turns off the activated EGFR pathway." (PMID 21722395, 2011). "Growth factor-driven MSC migration can be blocked using antibodies against PDGF, EGF, and VEGF in an orthotopic mouse pancreatic cancer model." (PMID 24212642, 2011). "EGF and neuropeptides like bombesin, cholecystokinin, neuromedin N and NT may act as growth factors and stimulate proliferation on the one hand and/or affect other cellular functions in different tumor cell types, including pancreatic cancer, on the other hand." (PMID 24212612, 2011). "EFEMP1 contains repeated EGF modules and was shown to activate AKT signaling via binding to EGFR in pancreatic carcinoma cells." (PMID 21955618, 2011). "The same results were obtained in other two pancreatic cancer cells, SW1990 and CFPAC-1, but the EGF-induced HCCR-1 expression was much significant in PANC-1 cells (data not shown)." (PMID 20423485, 2010). "Pancreatic cancer cells secrete LTB4 and produce growth factors such as epidermal growth factor (EGF)." (PMID 18781173, 2008).
pancreatic cancer (continued). "We found specific migration of MSC towards growth factors present in pancreatic tumours, such as PDGF, EGF, VEGF and specific inhibitors Glivec, Erbitux and Avastin interfered with migration." (PMID 18665180, 2008). "Epidermal growth factor (EGF) and its receptor are over expressed in pancreatic cancer, and expression correlates with invasion and metastasis." (PMID 15801978, 2005). "It has been shown previously that a variety of growth factors such as FGF-2, EGF, HB-EGF, and IGF-1 are over expressed in pancreatic cancer and that they have the potential to act as mitogens for pancreatic cancer cell lines." (PMID 15817123, 2005). "Comprehensive mRNA analysis of several growth factors in pancreatic cancer, including TGF-β, CTGF, aFGF, bFGF, PDGF A, PDGF C and EGF, resulted in the finding that TGF-β is likely to be a potent inducer of the desmoplastic reaction." (PMID 15365564, 2004). "Notably, the expression of epidermal growth factor (EGF) and its receptor (EGFR) as prognostic factors are reported in certain pancreatic cancer patients." (PMID 37371811, 2023). "Images were acquired at 0 h and 24 h of EGF treatment (1 ng/mL) alone and combined to treatment with erlotinib, an EGFR kinase activity inhibitor used in therapy of NSCLC and pancreatic cancer, to test the effect of Sorcin silencing in EGFR-dependent migration on H1299 cells." (PMID 37442828, 2023). "Upon EGF treatment, overexpression of miR-338-5p not only downregulated EGFR expression and inhibited MAPK/ERK signaling, but also inhibited EMT and metastasis process of pancreatic cancer (PC) cells." (PMID 33937024, 2021). "Considering the importance of EGF- AMPK-Skp2-Akt signal pathway in tumorigenesis, metastasis and invasion, IATL may provide a promising medicine for pancreatic cancer." (PMID 33661942, 2021). "Moreover, CALR promotes epidermal growth factor (EGF)-triggered EMT via the Integrin/EGFR/ERK/MAPK pathway and alters intracellular Ca2+ levels in the pancreatic cancer cells." (PMID 33221760, 2020). "Our study contained an important distinction from many previous pancreatic cancer studies examining EGFR inhibition in that we did not add exogenous EGF." (PMID 30921351, 2019). "High glucose-induced epidermal growth factor (EGF) expression and EGFR transactivation may increase pancreatic cancer cell proliferation." (PMID 31337431, 2019). "EGFR is highly conserved in pancreatic cancer tissues and EGFR inhibition has been shown to be an effective therapeutic strategy against pancreatic cancer, since the EGF/EGFR pathway activates downstream pro-oncogenic signaling pathways, resulting in proliferation and metastasis of cancer cells." (PMID 31572065, 2019). "PDPK1, one of the members of an upregulated EGF-signaling network in LRCC, mediates resistance to gemcitabine, is found to be dysregulated in pancreas cancer specimens, and might be an attractive molecular target for combination therapy studies." (PMID 30064387, 2018). "Our results reveal a novel mechanism to disengage the negative feedback of EGF signal pathways during pancreatic cancer cell proliferation." (PMID 30464258, 2018). "EGFR and its ligands, epidermal growth factor (EGF) and tumor growth factor-α (TGF-α), are coexpressed in the cells, which may contribute to the aggressiveness of pancreatic cancer by continuous EGFR signaling." (PMID 30400136, 2018). "Both compounds had EC50 in the low micromolar range for inhibition of PAK1 binding to Rac1 present in the EGF-stimulated CD18/HPAF cells, suggesting that compounds #1 and #6 will be effective in the inhibition of sustained hyper-activation of Rac1 seen in pancreatic cancer cells." (PMID 28410221, 2017). "To determine whether this is also true in pancreatic tumor, we treated three different types of PDAC cells (L3.6, BxPC3, and DanG) with EGF, and then analyzed the cell lysates using an antibody specifically recognizing Y639-phosphorylated (pY639) PIPKIγ." (PMID 28388589, 2017).
pancreatic cancer (continued). "New treatments targeting known oncogenes, or growth factors, in pancreatic cancer such as K-Ras, vascular endothelial growth factor (VEGF) and epidermal growth factor (EGF)/epidermal growth factor receptor (EGFR) have mostly failed and do not provide survival benefits." (PMID 27240340, 2016). "Pathway analysis of its target genes via DAVID showed enrichment (FDR < 5 %) of genes in the Jak-Stat signaling pathway, including several receptors of interleukins (PTPN6, IL22RA1, CREBBP, IL28RA, IL15RA, PIK3R5, STAT3) and pancreatic cancer pathways (VEGFC, ACVR1B, PIK3R5, EGF, STAT3)." (PMID 26572553, 2015). "The observation that EGF levels correlated with the degree of lymph node metastasis is consistent with widespread evidence implicating EGF signaling in cancer progression and metastasis, culminating in a phase three trial employing EGFR inhibition in pancreatic cancer." (PMID 26498838, 2015). "In EGF-STAT1 and EGF-STAT3, both gene pairs are involved in pancreatic cancer, EGF pathway, and signal transduction pathway; both STAT1 and STAT3 are activated by the Jak kinase in response to EGF, where JAK2/STAT3 signaling is required for EGF-driven ovarian cancer." (PMID 23940583, 2013). "While epidermal growth factor (EGF) had a similar result on the cells as wounded media (data not shown), incubation with conditioned media from pancreatic cancer cells (Panc-1) did not enhance the invasiveness of palladin-expressing cells." (PMID 22291919, 2012). "A 12-fold increase of miR155 expression level was observed following EGF treatment, but no change was found for miR200c, which had been reported to be downregulated in pancreatic cancer and other solid tumours." (PMID 23284982, 2012). "Many oncogenic molecular pathways including EGF/EGFR, Ras-Raf-MEK, PI3K/Akt, JAK/STAT, p16INK4A/retinoblastoma, Smad4/TGF-β, and hedgehog signaling pathways, have been reported to be involved in the pathogenesis of pancreatic cancer." (PMID 22348037, 2012). "Growth factors, such as PDGF, EGF, and VEGF drive mobilization of MSC toward the pancreatic tumor." (PMID 24212642, 2011). "Since EGF, TGF-alpha and IGF-1 are considered to play an important role in the proliferation of pancreatic cancer cells, we studied the effects of tyrphostins on the growth of three human pancreatic cancer cell lines (MiaPaCa-2, Panc-1 and CAV)." (PMID 8260363, 1993). "However, TMEM16A modifies the pattern of EGF-induced phosphorylation of EGFR without affecting Akt or Erk phosphorylation in pancreatic cancer." (PMID 37309001, 2023). "Thus, we further investigated whether EGF signaling pathway contributes to KLK8-induced proliferation and anti-apoptotic effects in pancreatic cancer cells." (PMID 34395235, 2021). "Another human RNase called hRNase 5 acts as an EGFR ligand and a serum biomarker to predict EGFR inhibitor response in pancreatic cancer, but EGF fails to have such predictive function although the binding affinity of hRNase 5 to EGFR is about 23-fold less than EGF for EGFR binding." (PMID 33986289, 2021). "The inhibitory effect of IATL on both EGF and SKP2 may offer a novel option for pancreatic cancer." (PMID 33661942, 2021). "Resveratrol exhibited reprogramming of EMT into MET in pancreatic cancer via suppression of AKT signaling pathways and prevented EGF-mediated activation of EMT in the ER-positive breast cancer cell line (MCF-7) through suppression of the EGF-activated Erk pathway." (PMID 34220337, 2021). "The use of a tailored protein fusion between epidermal growth factor (EGF; targeting component) and TAU (effector component) resulted in a cytostatic and apoptotic response in epidermal growth factor receptor (EGFR)-positive pancreatic cancer cells, a finding confirmed in other models." (PMID 33207722, 2020). "Taken together, the anti-hMUC1 monoclonal antibody suppressed EGF-mediated signaling in MUC1 expressing pancreatic tumor cells even though we could not detect its growth-suppressive effect in vitro." (PMID 29987260, 2018).
pancreatic cancer (continued). "In addition, EGF induces the expression and activation of ICE in pancreatic carcinoma cells." (PMID 23383347, 2013). "In patients with primary pancreatic cancer, circulating levels of VEGF (p < 0.0001) were significantly increased compared to healthy control subjects, whereas circulating levels of PDGF-AA (p < 0.0001), Ang-1 (p = 0.002) and EGF (p < 0.0001) were significantly decreased." (PMID 21729304, 2011). "Additionally, high glucose levels induce epidermal growth factor (EGF) expression and epidermal growth factor receptor (EGFR) transactivation, a well-known oncogenic pathway, in pancreatic cancer cell lines which may increase pancreatic cancer cell proliferation." (PMID 39410536, 2024). "Moreover, TSPAN6 overexpression reduced EGF-dependent invasion using transwell migration assays; in vitro scratch assays further confirmed that TSPAN6 overexpression in these K-RAS activating mutant pancreatic cancer cells leads to impaired epithelial sheet migration." (PMID 35184157, 2022). "We first analyzed by RPPA a series of signalling pathways in pancreatic cancer cells, expressing or not expressing SMAD4, and repeatedly stimulated with EGF “in vitro” in order to simulate “in vivo” conditions." (PMID 27655713, 2016). "In order to examine whether or not EGF and ROCK are involved in pancreatic cancer cell proliferation, we first evaluated BrdU incorporation in Panc1, KP3 and AsPc1 cells utilizing Y27632 as a specific ROCK inhibitor." (PMID 21722395, 2011). "Similarly, carcinogen-induced pancreatic cancer in the hamster and rat expressed only TGFα and EGFR, but not EGF." (PMID 16822304, 2006). "Moreover, in an isogenic pancreatic cancer cell line with CRISPR-Cas9-mediated knockout of SHP2, tyrosyl phosphorylation of endogenous KRAS Q61H was observed even in the absence of EGF treatment, which is consistent with the notion that SHP2 is involved in dephosphorylating endogenous KRAS." (PMID 34725361, 2021).
glioblastoma (174 papers, 2006 to 2026). The most malignant astrocytic tumor (WHO grade IV). "We recently designed and engineered an oHSV, named R-613, completely detargeted from its natural receptors, and retargeted to EGFRvIII, a mutated form of the epidermal growth factor, typical of human glioblastoma." (PMID 34578259, 2021). "Among the growth factors potentially involved in the migratory capability of GBM, the most studied is the EGF, since its receptor has been demonstrated to be over-expressed or mutated in a large percentage (40%) of glioblastomas." (PMID 24023874, 2013). "The tyrosine-phosphoproteome in the cells with highly expressed EGF receptor variant III (EGFRvIII), the most common variant of the EGF receptor observed in glioblastoma multiforme, were quantitatively analyzed upon EGF stimulation." (PMID 22912867, 2012). "Because work in glioblastoma has suggested that PKM2 is required for β-catenin activation downstream of EGF stimulation in that tissue, we determined whether loss of PKM2 impacted β-catenin localization in tumors arising in Apcflox/flox;Pkm2flox/flox mice." (PMID 29214019, 2017). "Taking into consideration that PIBF acts as a transcriptional factor, we suggest a possible role of PIBF in regulating the expression of several target genes such as IL-6 and EGF that could be associated with the invasive effects of glioblastoma cells." (PMID 28168193, 2017). "It is noteworthy that monochloro-GM3 inhibited the activation of ΔEGFR, which is commonly expressed in glioblastomas (the most aggressive type of brain tumor in humans) and whose continuous EGF-independent activation is associated with greatly enhanced malignant behavior." (PMID 24944646, 2014). "Since EGFR is amplified and/or mutated in 45% of all glioblastoma tumors, we also examined whether RhoG mediates EGF-stimulated signaling in glioblastoma cells." (PMID 22966858, 2012). "Glioblastoma (GBM), a highly lethal primary brain tumor, expresses epidermal growth factor (EGFR), which is implicated in tumor proliferation and migration." (PMID 33959279, 2021). "We have successfully applied the model to identify the interconnections altered in the constitutive signaling of the mutated EGFR in glioblastoma multiforme (GBM) compared to EGF-dependent and wild-type EGFR (EGFRwt) signaling." (PMID 31386654, 2019). "Stimulation of human glioblastoma multiforme (GBM) cells with epidermal growth factor (EGF) causes phosphorylation of PKM2 at serine (Ser) residue 37 and translocation of the PKM2 protein to the nucleus." (PMID 27340866, 2016). "The smaller hub, GSK-3β, integrates signals from mutations in NF1 and PTEN, as well as from the Wnt, sortilin, and EGF pathways, playing an important role in glioblastoma pathogenesis." (PMID 39857717, 2025). "In glioblastoma cells, EGF treatment promotes GDH1 expression through the MEK/ERK/ELK1 pathway, stimulating glutaminolysis and incorporation of glutamine carbons into TCA cycle intermediates." (PMID 39433211, 2025). "In another study, freshly resected glioblastoma multiforme cells were grown in a special serum-free medium supplemented with EGF and FGF-2 or PDGFA alone." (PMID 38392188, 2024). "Overactive activation of the EGF signalling pathway is a crucial feature in glioblastoma, playing a pivotal role in the progression of the disease." (PMID 38687049, 2024). "EGFR’s most important ligands in glioblastoma include epidermal growth factor (EGF) and transforming growth factor-alpha (TGF-α)." (PMID 38928445, 2024). "The study highlighted the significance of the PI3K/Akt pathway in glioblastoma by demonstrating reduced motility and EGF stimulating properties in GBM cells treated with wortmannin, a PI3K inhibitor." (PMID 39267853, 2024). "Many CSC culture conditions also include supplements such as MSC stimulatory supplements for Ewing sarcoma CSCs and EGF, bFGF, and B27 for glioblastoma and rhabdomyosarcoma CSCs." (PMID 36506091, 2022).